CCDC88C (coiled-coil and HOOK domain protein 88C)
Description:
Required for activation of guanine nucleotide-binding proteins (G proteins) during non-canonical Wnt signaling. Binds to ligand-activated Wnt receptor FZD7, displacing DVL1 from the FZD7 receptor and leading to inhibition of canonical Wnt signaling. Acts as a non-receptor guanine nucleotide exchange factor by also binding to guanine nucleotide-binding protein G(i) alpha (Gi-alpha) subunits, leading to their activation. Binding to Gi-alpha subunits displaces the beta and gamma subunits from the heterotrimeric G protein complex, triggering non-canonical Wnt responses such as activation of RAC1 and PI3K-AKT signaling. Promotes apical constriction of cells via ARHGEF18.
Synonyms: HkRP2; DAPLE; KIAA1509; SCA40; HYC1
Tractability: Antibody: its Gene Ontology location is reachable by antibodies, with medium confidence. PROTAC: ubiquitination databases record sites on it; its protein half-life has been measured.
Gene: Protein-coding gene on chromosome 14 (91,271,323 to 91,417,844, reverse strand). Ensembl gene ENSG00000015133.
Subcellular location: Cytoplasm; Cell junction
Subcellular location (Human Protein Atlas): Cell Junctions
Pathways (Reactome):
Signal Transduction: Negative regulation of TCF-dependent signaling by DVL-interacting proteins
Gene Ontology:
Molecular function: frizzled binding; G-protein alpha-subunit binding; guanyl-nucleotide exchange factor activity; protein binding; dynein light intermediate chain binding; identical protein binding; microtubule binding; PDZ domain binding; protein dimerization activity
Biological process: apical constriction; negative regulation of canonical Wnt signaling pathway; non-canonical Wnt signaling pathway; positive regulation of JNK cascade; small GTPase-mediated signal transduction; cytoplasmic microtubule organization; cytoskeleton-dependent intracellular transport; protein destabilization; signal transduction
Cellular component: anchoring junction; cell junction; cytoplasm; centrosome; apical junction complex
Genetic constraint (gnomAD): Loss-of-function variants: 109 observed, 168.46 expected, observed/expected ratio (o/e) 0.65, 90% interval 0.55 to 0.76. The upper end of that interval is the gene's LOEUF score, 0.76, which puts it in group 3 of 6, group 1 being the genes least tolerant of losing a copy. Missense variants: 2,435 observed, 2,382.1 expected, observed/expected ratio (o/e) 1.02, 90% interval 0.99 to 1.06. Synonymous variants: 1,116 observed, 1,014.2 expected, observed/expected ratio (o/e) 1.1, 90% interval 1.05 to 1.16.
Homologues: Orthologues: chimpanzee CCDC88C (99% identical), macaque CCDC88C (98% identical), guinea pig CCDC88C (86% identical), dog CCDC88C (85% identical), rat Ccdc88c (84% identical), pig CCDC88C (83% identical), mouse Ccdc88c (82% identical), tropical clawed frog ccdc88c (58% identical), zebrafish ccdc88c (52% identical), Drosophila melanogaster Girdin (21% identical), Caenorhabditis elegans grdn-1 (17% identical). Paralogues in human: CCDC88A (44% identical), CCDC88B (21% identical), HOOK3 (11% identical), HOOK1 (10% identical), HOOK2 (10% identical).
Diseases named in the same sentence as CCDC88C in open-access papers:
CCDC88C is named in the same sentence as 22 diseases in open-access papers, as found by Europe PMC text mining. Sharing a sentence is not in itself a finding about the gene and the disease. The quoted sentences say what the papers report.
Hydrocephalus (10 papers, 2018 to 2024). Hydrocephalus is an active distension of the ventricular system of the brain resulting from inadequate passage of CSF from its point of production within the cerebral ventricles to its point of absorption into the systemic circulation. "Knockout of Daple, a Dvl-associated protein with high leucine content (Ccdc88c), caused hydrocephalus and disorientation of ependymal cilia." (PMID 37008045, 2023). "We identified rhythmically expressed genes, which have been associated with developmental processes, such as hydrocephalus-associated genes (Ccdc88c, Hydin), and several rhythmically expressed mitogens, which are likely diurnally released into CSF (Wnt5b, Angpt1-2, Ccn2)." (PMID 38802875, 2024). "Recently, two autosomal recessive forms of hydrocephalus have been linked to mutations in MPDZ and CCDC88C that encode a tight junction protein (MUPP-1) and a regulator of cell migration (DAPLE), respectively." (PMID 35096710, 2021). "Nonsyndromic hydrocephalus includes the classical X‐linked type associated with mutations in L1CAM (MIM 307000) and autosomal recessive hydrocephalus related to the gene CCDC88C (HYC1, MIM 236600), MPDZ (HYC2, MIM 615219), and WDR81 (HYC3, MIM 617967)." (PMID 33724704, 2021). "The hydrocephalus observed in carriers of CCDC88C mutations resulted presumably from a dysfunction of Wnt non‐canonical signaling, because these mutations truncate the C‐terminus of DAPLE, the protein it encodes, disabling its binding to the PDZ domain of DVL." (PMID 30518636, 2019). "Two of the known human hydrocephalus genes, CCDC88C and MPDZ, were identified in the microarray." (PMID 30190587, 2018). "CCDC88C encodes DAPLE protein and acts as a negative regulator of the non-canonical wingless/integrated (WNT) signaling pathway; its mutation results in hydrocephalus through defective cilia orientation and aberrant CSF flow." (PMID 35047005, 2021).
congenital hydrocephalus (7 papers, 2015 to 2024). Hydrocephalus that is present at birth. "Ccdc88c (coiled-coil domain containing 88 C, or Daple) is a gene whose mutation causes congenital hydrocephalus." (PMID 38802875, 2024). "Mutations in the Wnt pathway inhibitor gene CCDC88C (2.57-fold higher expression in B6, but only differentially expressed in the nm1054 comparison) have been shown to result in non-syndromic congenital hydrocephalus in human patients and a mouse model." (PMID 30190587, 2018). "Genetic heterogeneity of congenital hydrocephalus is observed: mutations in the CCDC88C gene [MIM:611204] on chromosome 14 and in the MPDZ gene [MIM:603785] on chromosome 9 are responsible for autosomal recessive hydrocephalus (respectively HYC1 [MIM:236600] and HYC2 [MIM:615219])." (PMID 26452345, 2015). "Other mutations associated with congenital hydrocephalus include multiple-PDZ domain protein-1 (MUPP-1), a tight junction protein, and CCDC88C (DAPLE) mutations of the Wnt signaling pathway." (PMID 39767835, 2024).
breast carcinoma (3 papers, 2013 to 2024). "Dysregulated expression of CCDC88C was observed in lymph node metastatic tumor tissues of breast cancer." (PMID 38971758, 2024). "In our study, the genes regulated by CCDC88C in breast cancer were also enriched in regulation of microtubule cytoskeleton organization, highlighting the importance of CCDC88C in regulation of actin cytoskeleton." (PMID 38971758, 2024). "Analysis of protein abundance correlation based on the cProSite database showed that there was a positive correlation (R = 0.4431, p < 0.0001) between GALNT6 and CCDC88C protein abundance in the normal breast and breast cancer tissues." (PMID 38971758, 2024). "A microarray dataset GSE30480 revealed that CCDC88C expression was higher in lymph node metastatic tissues than in primary tumor tissues from breast cancer patients." (PMID 38971758, 2024). "We identified that CCDC88C was dysregulated during breast cancer metastasis and its high expression was related to a poor prognosis of lymph node metastatic breast cancer patients." (PMID 38971758, 2024). "Next, we further explored the role of CCDC88C in breast cancer metastasis in vivo." (PMID 38971758, 2024). "Overexpression of CCDC88C promoted the migration and invasive abilities of breast cancer cells." (PMID 38971758, 2024). "Our data also suggest that the function of CCDC88C in breast cancer metastasis requires CEMIP." (PMID 38971758, 2024). "In summary, our data emphasize the essential role of CCDC88C in breast cancer metastasis." (PMID 38971758, 2024).
Ataxia (2 papers, 2022 to 2023). Ataxia refers to impaired coordination of voluntary muscle movement. "Here, we describe a novel missense CCDC88C mutation (p.R203W) in the hook domain of the DAPLE protein encoded by the CCDC88C gene that was identified in a female patient who developed late-onset ataxia, dysmetria and intention tremor." (PMID 36768938, 2023). "We identified a novel missense CCDC88C mutation (c.607C > T) resulting in an p.R203W substitution in the hook domain of the DAPLE protein in a Hungarian female patient presenting late-onset ataxia." (PMID 36768938, 2023). "Spinocerebellar ataxia (SCA) 40 is an extremely rare subtype of the phenotypically and genetically diverse autosomal dominant ataxias caused by mutations of the CCDC88C gene." (PMID 36768938, 2023).
colorectal cancer (2 papers, 2024). A primary or metastatic malignant neoplasm that affects the colon or rectum. "In colorectal cancer, CCDC88C is highly expressed in metastasized tumor cells of patients, and its high expression is linked to a poor prognosis for patients with metastatic colorectal cancer, implying that CCDC88C may be involved in tumor metastasis in colorectal cancer." (PMID 38971758, 2024). "Abnormal expression of CCDC88C is also found in colorectal cancer progression, and CCDC88C triggers gastric cancer, colorectal cancer, and cervical cancer cell migration." (PMID 38971758, 2024). "However, CCDC88C also acts as a tumor suppressor, which inhibits colorectal cancer and cervical cancer cell proliferation." (PMID 38971758, 2024). "Coiled-coil domain containing 88C (CCDC88C) is a component of non-canonical Wnt signaling, and its dysregulation causes colorectal cancer metastasis." (PMID 38971758, 2024).
epilepsy (1 paper, 2024). A brain disorder characterized by episodes of abnormally increased neuronal discharge resulting in transient episodes of sensory or motor neurological dysfunction, or psychic dysfunction. "PDZ3 of MPDZ interacts with DAPLE (encoded by CCDC88C) that is associated with neurodegenerative diseases, congenital hydrocephalus, and epilepsy in an autosomal dominant/recessive inheritance, potentially explaining the heterozygous variants associated with febrile seizures." (PMID 38292201, 2024).
melanoma (1 paper, 2020). A malignant, usually aggressive tumor composed of atypical, neoplastic melanocytes. "Ccdc88c is a hub gene whose expression in circulating tumor cells is associated with melanoma survival." (PMID 32831131, 2020).
metastatic cancer (1 paper, 2024). A carcinoma which has spread from the original site of growth to another anatomic site. "It is speculated that aberrant expression of CCDC88C may play an important role in metastatic cancer and enhance tumor cells to spread around the body." (PMID 38971758, 2024).
cancer (5 papers, 2014 to 2025). A tumor composed of atypical neoplastic, often pleomorphic cells that invade other tissues. "Interestingly, genes such as CCDC88C, CD200R1, and CUL3 have been associated with prognosis or being highly expressed in other forms of cancer, however they have not been reported in PDAC to the best of our knowledge." (PMID 25180633, 2014). "Six of the 10 remaining genes, despite not being listed, were genes for which literature search supported undeniable oncogenic properties (STIM2, ARHGAP24, KLF12, KMT2C, CCDC88C and DOCK11), and 4 genes were—to our knowledge—not previously reported in cancer, yet may include new candidate drivers." (PMID 28534499, 2017).
CCDC88C also shares sentences with these, for which no sentence is quoted: tumor (7 papers); cervical cancer (1); colon cancer (1); communicating hydrocephalus (1); deafness (1); gastric cancer (1); hydrops fetalis (1); Intention tremor (1); lung carcinoma (1); metastatic colorectal cancer (1); metastatic tumors (1); myeloid neoplasm (1); neurodegenerative disease (1).